COL13A1 (collagen type XIII alpha 1 chain)
Diseases named in the same sentence as COL13A1 in open-access papers:
COL13A1 is named in the same sentence as 47 diseases in open-access papers, as found by Europe PMC text mining. Sharing a sentence is not in itself a finding about the gene and the disease. The quoted sentences say what the papers report.
osteosarcoma (5 papers, 2022 to 2025). A usually aggressive malignant bone-forming mesenchymal neoplasm, predominantly affecting adolescents and young adults. "COL13A1 showed elevated expression in osteoblastic osteosarcoma cells, cancer-associated fibroblasts (CAFs), and endothelial cells (ECs)." (PMID 41312374, 2025). "For osteosarcoma, COL13A1 was a risk factor and the other four genes were protective factors." (PMID 36035315, 2022). "Emerging single-cell RNA sequencing evidence indicated that COL13A1 is highly expressed in osteosarcoma and likely promotes tumor progression." (PMID 41312374, 2025). "Since COL13A1 is predominantly expressed in osteoblastic osteosarcoma cells, this study employed two osteoblastic osteosarcoma cell lines (143B and HOS) to investigate the effects of COL13A1 knockdown or overexpression on osteosarcoma progression." (PMID 41312374, 2025). "In research of identifying survival-related genes in osteosarcoma, COL13A1 and CTNNBIP1 were also included as prognostic biomarkers." (PMID 36035315, 2022). "•The study confirmed the role of COL13A1 in osteosarcoma progression." (PMID 41312374, 2025). "While this study demonstrated the role of COL13A1 via TGF-β axis in osteosarcoma, we acknowledge that tumor heterogeneity across histological subtypes may influence its functional outcomes." (PMID 41312374, 2025). "•COL13A1 effectively promoted osteosarcoma proliferation, metastasis, and bone destruction." (PMID 41312374, 2025). "•Through WGCNA of the TARGET-OS cohort, COL13A1 emerged as a prognostic gene in osteosarcoma." (PMID 41312374, 2025). "In addition, effects of DNA methylation inhibitors on osteosarcoma cell phenotype and prognosis in animal models targeting the three identified genes (COL13A1, MXI1, and TBRG1) deserve further study." (PMID 35602303, 2022). "Similarly, several survival-related genes, including MUC1, COL13A1, KAZALD1, and JAG2, were identified as prognostic markers in osteosarcoma by scRNA-seq and TARGET analysis." (PMID 39324133, 2024). "Finally, a 5-gene prognostic model consisting of COL13A1, TNFRSF1A, LILRA6, CTNNBIP1, and CD180 was established for predicting the prognosis of osteosarcoma." (PMID 36035315, 2022). "Three genes, including COL13A1, MXI1, andTBRG1, could be used as DNA methylation biomarkers of accurate diagnosis and therapy for osteosarcoma in the future." (PMID 35602303, 2022). "The three genes (COL13A1, MXI1, and TBRG1) regulated by DNA methylation were identified to relate with the outcomes of OS patients, which might provide a new insight to the pathological mechanism of osteosarcoma." (PMID 35602303, 2022).
bladder cancer (4 papers, 2017 to 2022). "And studies have shown that urinary COL13A1 protein content can act as an independent risk factor for bladder cancer recurrence." (PMID 35602303, 2022). "COL13A1 in urine may be a potential diagnostic and prognostic biomarker for bladder cancer." (PMID 35602303, 2022). "In previous studies of bladder cancer, silencing of COL13A1 changed the invasion patterns of infiltration and decreased invasion capability through decreased invadopodium." (PMID 36010952, 2022). "They discovered that COL4A1+COL13A1 was an independent predictor for intravesical recurrence of bladder cancer." (PMID 36035315, 2022). "It is also suggested that COL13A1 expression in voided urine can be used as a prognostic factor for bladder cancer." (PMID 36010952, 2022). "Novel small-molecule inhibitors, neutralizing antibodies, or anti-sense nucleotides disrupting COL4A1 and COL13A1 should be developed and tested in patients with bladder cancer refractive to conventional therapies." (PMID 28415608, 2017).
breast cancer (4 papers, 2019 to 2023). A primary or metastatic malignant neoplasm involving the breast. "This is reflected in our 18-gene signature, with three of five RNAs upregulated in PAFs and for which higher expression in breast cancers was associated with poor prognosis encoded collagen proteins (Col5a2, Col13a1, Col18a1)." (PMID 34565423, 2021). "High expression of COL13A1 was observed in breast cancer cells, correlated with invasive tumor growth, and induced anoikis resistance." (PMID 36035315, 2022). "Although Col13a1 and Spock2 mRNA abundance showed trends towards up- and downregulation respectively in mammary tumours with metastases, this was not significant and will need to be reassessed in a larger independent cohort." (PMID 37402051, 2023).
congenital myasthenic syndrome (3 papers, 2019 to 2022). Congenital myasthenic syndrome (CMS) is a group of genetic disorders of impaired neuromuscular transmission at the motor endplate characterized by fatigable muscle weakness. "Congenital myasthenic syndromes caused by mutations in the COL13A1 gene are very rare and have a phenotype described as severe." (PMID 35337379, 2022).
pulmonary fibrosis (3 papers, 2020 to 2023). Chronic progressive interstitial lung disorder characterized by the replacement of the lung tissue by connective tissue, leading to progressive dyspnea, respiratory failure, or right heart failure. "To study whether the lack of collagen XIII predisposes to restrictive lung disease, we exposed Col13a1-modified mice to bleomycin-induced pulmonary fibrosis." (PMID 38568728, 2023). "Induction of pulmonary fibrosis with bleomycin revealed similar increases in the modified Ashcroft score and 4-hydroxyproline content in Col13a1-modified mice to those in littermate wild-type controls." (PMID 38568728, 2023). "Based on these findings, we looked for CD82 protein expression in human pulmonary fibrosis (IPF), co-staining for pertinent markers of Pdgfra+ fibroblasts (PDGFR-α and COL13A1)." (PMID 32488016, 2020).
urothelial carcinoma (3 papers, 2019 to 2022). A malignant neoplasm derived from the transitional epithelium of the urinary tract (urinary bladder, ureter, urethra, or renal pelvis). "However, it has been reported that in urothelial carcinoma, the production of collagen type 13 alpha 1 (COL13A1) by tumor cells is closely related to tumor invasion." (PMID 35602303, 2022). "Studies of the Miyake laboratory demonstrated that the expression of COL13A1 and COL4A1 by cancer cells of human urothelial carcinoma plays a crucial role in tumor invasion through the induction of tumor budding." (PMID 31581653, 2019).
Cognitive impairment (2 papers, 2019). Abnormal cognition is characterized by deficits in thinking, reasoning, or remembering. "Mild to severe cognitive impairment has been reported in patients carrying mutations in the SLC5A7 gene, DPAGT1 gene, SNAP25 gene, COL13A1 gene, MYO9A gene, MUNC13–1 gene, and in SCN4A-related CMS." (PMID 30808424, 2019). "Finally, although less likely, cognitive deficits are relatively common in the general population, and their co-occurrence with COL13A1-CMS might be incidental." (PMID 31081514, 2019).
malignant neoplasm of the thyroid gland (2 papers, 2023 to 2026). "Previous research has highlighted collagen genes, such as COL13A1 and COL23A1, as key players in thyroid cancer." (PMID 42306204, 2026).
bladder tumors (1 paper, 2017). "IHC evaluation of human UCB tissues obtained from 97 patients revealed similar staining patterns for COL4A1 and COL13A1 as those in the orthotopic murine bladder tumors." (PMID 28415608, 2017). "Immunostaining analysis of orthotopic bladder tumors showed that both COL4A1 and COL13A1 were knocked down by intravesical treatment with COLs siRNA." (PMID 28415608, 2017). "The in vivo orthotopic experimental model of bladder tumors showed that intravesical treatment with siRNA targeting COL4A1 and COL13A1 inhibited the formation of the infiltrative pattern." (PMID 28415608, 2017).
glaucoma (1 paper, 2021). Increased pressure in the eyeball due to obstruction of the outflow of aqueous humor. "Regarding core ECM genes that were significantly altered only in CAβ3 cells, neither VWA5A (FC = 2.67) nor COL13A1 (FC = −1.64) have been found to be associated with glaucoma, although COL13A1 was differentially regulated in response to the steroid triamcinolone in cultured HTM cells." (PMID 34440692, 2021).
goiter (1 paper, 2024). Enlargement of the thyroid gland usually caused by lack of iodine in the diet, hyperthyroidism, or thyroid nodules. "COL13A1 expression in Graves’ disease and goiter thyroid samples was compared with TGF-β1 and TNF, and these were also studied in human thyroid epithelial cells and fibroblasts." (PMID 38564194, 2024). "The expression of COL13A1 in goiter samples correlated with levels of TGF-B1." (PMID 38564194, 2024).
intracerebral hemorrhage (1 paper, 2019). A cerebrovascular disorder characterized by bleeding into one or both cerebral hemispheres including the basal ganglia and the cerebral cortex. "Other studies found that the presence of the A→C polymorphism (rs942576) of COL13A1 was associated with the prevalence of intracerebral hemorrhage." (PMID 31581653, 2019).
ischemia (1 paper, 2022). A hypoperfusion of the BLOOD through an organ or tissue caused by a PATHOLOGIC CONSTRICTION or obstruction of its BLOOD VESSELS, or an absence of BLOOD CIRCULATION. "Contrarily, Col6a6, Col13a1, and Col25a1 genes showed no augmentation in mRNA expression at chronic phases of ischemia." (PMID 36555255, 2022).
Kyphoscoliosis (1 paper, 2019). An abnormal curvature of the spine in both a coronal (lateral) and sagittal (back-to-front) plane. "Joint laxity and kyphoscoliosis were reported in association with VAMP1 and COL13A1 variants." (PMID 30808424, 2019).
metastatic prostate carcinoma (1 paper, 2022). A carcinoma that arises from the prostate gland and has spread to other anatomic sites. "Through RNA sequencing analysis, we prove that COL13A1, which is a key factor for the progression of metastasis, is closely related to metastatic prostate cancer." (PMID 36010952, 2022).
metastatic tumours (1 paper, 2020). "Moreover, ADAM22 expression correlated with known brain metastatic associated in both primary (MOCS1, n = 21, p < 0.05) and metastatic tumours (MOCS1, COL13A1, TLR4, HBEGF and PELI2, n = 21, p < 0.05)." (PMID 33208158, 2020).
non-small cell lung carcinoma (1 paper, 2025). A group of at least three distinct histological types of lung cancer, including non-small cell squamous cell carcinoma, adenocarcinoma, and large cell carcinoma. "A similar mechanism exists in non-small cell lung cancer (NSCLC), where CAFs overexpressing COL13A1 recruit TAMs and Tregs by secreting chemokines and simultaneously inhibit dendritic cells (DCs) and cytotoxic T-cell infiltration." (PMID 41226585, 2025).
osteoporosis (1 paper, 2022). A condition of reduced bone mass, with decreased cortical thickness and a decrease in the number and size of the trabeculae of cancellous bone (but normal chemical composition), resulting in increased fracture incidence. "Moreover, overexpression of COL13A1 showed significant bone overgrowth, followed by severe osteoporosis, in a mouse model." (PMID 36010952, 2022).
Parkinson disease (1 paper, 2017). A progressive degenerative disorder of the central nervous system characterized by loss of dopamine producing neurons in the substantia nigra and the presence of Lewy bodies in the substantia nigra and locus coeruleus. "A second archaic GEA locus that is associated with changed expression of COL13A1 includes rs17497526 (hg19, chr10:71580120), an allele associated with Parkinson’s disease risk in North Americans." (PMID 28366169, 2017).
prostate carcinoma (1 paper, 2022). A carcinoma that arises from epithelial cells of the prostate gland. "To evaluate the expression of COL13A1 and confirm that it is associated with metastatic bone lesions in human prostate cancer, we used an open GEO database." (PMID 36010952, 2022). "Using the open database GEO, we also confirmed that the expression of COL13A1 was higher in bone metastatic prostate cancer tissue than in localized prostate cancer tissue in patients." (PMID 36010952, 2022). "Through analyzing the transcriptomic profiling of DEGs, we found COL13A1 upregulated in hypoxia-treated prostate cancer cells." (PMID 36010952, 2022). "Furthermore, using the open database GEO, we also confirmed that the expression of COL13A1 was higher in bone metastatic prostate cancer tissue than in localized prostate cancer tissue in patients." (PMID 36010952, 2022). "Therefore, COL13A1 was highly correlated with the metastasis of prostate cancer." (PMID 36010952, 2022). "Therefore, COL13A1 may be closely related to the bony metastasis of prostate cancer, and our findings may provide valuable information on the pathophysiology of the metastatic niche induced by hypoxia in patients with CRPC." (PMID 36010952, 2022). "Thus, COL13A1 induced by hypoxic stress may play a role in cell migration, adhesion, and infiltration to bones, the most common site where metastases occur in advanced prostate cancer." (PMID 36010952, 2022). "Since the expression of COL13A1 was increased in PC3 cell lines that were derived from bone metastatic prostate cancer in RT-PCR, we can infer that COL13A1 may be closely related to the bony metastasis of prostate cancer." (PMID 36010952, 2022).
ptosis (1 paper, 2019). The drooping of the upper eyelid. "Unlike other CMS, ptosis in patients with COL13A1-CMS is non-fluctuating and non-fatigable on examination in adulthood, compared to an early age." (PMID 31081514, 2019).
seminoma (1 paper, 2025). A radiosensitive malignant germ cell tumor found in the testis (especially undescended), and extragonadal sites (anterior mediastinum and pineal gland). "A recent research also indicated that COL13A1 contributed to the relapse of the seminoma, which implied that COL13A1 might be an important biomarker in multiple tumors." (PMID 41312374, 2025).
tumor (12 papers, 2009 to 2026). "The present study investigated the association of COL4A1 and COL13A1 with tumor invasion and progression using in vitro and in vivo experimental models and clinical materials of human UCB." (PMID 28415608, 2017). "Expression levels vary by sample type, tumor stage, and histology, with higher COL13A1 staining intensity and moderate COL23A1 staining observed in tumors." (PMID 42306204, 2026). "COL4A1 and COL13A1 predominantly localized to the stromal area around the tumor site and the cytoplasm of tumor cells, respectively." (PMID 28415608, 2017). "COL4A1 and COL13A1 production by cancer cells plays a pivotal role in tumor invasion through the induction of tumor budding." (PMID 28415608, 2017). "Finally, the low expression of COL13A1 limited the weight and lung metastasis of tumor, and reduced bone destruction in the orthotopic tumor-bearing model." (PMID 41312374, 2025). "Furthermore, we observed that the genes associated with tumour poor prognosis, KRT7 and COL13A1,65, 66, 67 exhibited chromatin accessibility in C1 and C2." (PMID 39210544, 2024). "Thus, COL4A1 and COL13A1 production in cancer cells supports their high invasion capability into the bladder wall and promotes subsequent tumor progression and metastasis in orthotopic bladders." (PMID 28415608, 2017). "Besides, high expression of COL13A1 was related to the poorer immunotherapy response, indicating that COL13A1 might regulate tumor immunotherapy." (PMID 41312374, 2025). "COL4A1 and COL13A1 expression was notably increased in the trabecular and infiltrative patterns compared with that in the nodular pattern (P = 0.017 and 0.012, respectively), implying that the expression of these two collagens increases biological aggressiveness and tumor invasiveness in human UCB." (PMID 28415608, 2017). "COL13A1 was significantly upregulated, while COL23A1 was downregulated in tumor tissues compared to normal tissues." (PMID 42306204, 2026). "We found that the expression levels of seven integrin ligands (COL4A6, COL13A1, FGB, COL19A1, COL18A1, COL14A1, and COL11A2) were negatively correlated with the Gleason score, suggesting that the suppression of integrins and/or their ligands is associated with more advanced tumor grade." (PMID 19653896, 2009).
cancer (6 papers, 2017 to 2025). A tumor composed of atypical neoplastic, often pleomorphic cells that invade other tissues. "To further evaluate whether COL13A1 is associated with cancer cell migration, we firstly confirmed the expression of COL13A1 by PCR." (PMID 36010952, 2022). "Cancer cell migration was promoted in 22Rv1-CI compared to controls, and the expression of COL13A1 was significantly up-regulated in 22Rv1-CI according to differentially expressed gene analysis of RNA sequencing among groups." (PMID 36010952, 2022). "By silencing COL13A1 activity with si-RNA, we discovered that the migration of cancer cells significantly decreases." (PMID 36010952, 2022). "Upregulation of COL13A1 is closely related to metastasis formation in some cancers." (PMID 36839934, 2023). "Cancer cell migration was impeded in a wound healing assay after transfecting si-COL13A1." (PMID 36010952, 2022). "Additionally, to further understand the effect of COL13A1 on cancer cell viability, an MTT assay was performed after si-COL13A1 transfection to each group for 24 h and 48 h." (PMID 36010952, 2022).
infection (3 papers, 2024 to 2025). The state of being infected such as from the introduction of a foreign agent such as serum, vaccine, antigenic substance or organism. "Genes involved in cell adhesion and structural components, including laminins (LAMA2), elastin (ELN), and collagens (COL16A1, COL13A1, COL8A1) were significantly downregulated at 24 hours post-infection (hpi) in both variants." (PMID 41200555, 2025).
COL13A1 also shares sentences with these, for which no sentence is quoted: cervical cancer (2 papers); channelopathies (1); coeliac disease (1); COVID-19 (1); esophageal squamous cell carcinoma (1); gastric cancer (1); Graves disease (1); heart failure (1); hyperthyroidism thyrotoxicosis (1); lung carcinoma (1); melanoma (1); muscular dystrophies (1); myopathies (1); neurodegenerative disease (1); ovarian carcinoma (1); restrictive lung disease (1); Stroke (1); thyroid cancer (1); triple-negative breast carcinoma (1); Urethral stricture (1); urothelial carcinoma of the bladder (1); Uterine leiomyoma (1).